CHD8 (chromodomain helicase DNA binding protein 8)
Diseases named in the same sentence as CHD8 in open-access papers (continued):
Sharing a sentence is not in itself a finding about the gene and the disease.
Anxiety (continued). "Chd8 heterozygous mutant mice have been found to manifest macrocephaly, increased anxiety-like behavior, altered social behavior, and cognitive deficits, but the behavioral phenotypes of different Chd8 mutant mouse lines generated by different groups overlap only partially." (PMID 37268684, 2023). "Our results suggest that CHD8 in the adult brain may contribute to the control of social behavior and anxiety-like behavior." (PMID 37268684, 2023). "The Chd8+/− mice showed a decreased proportion of time in the center in the open-field test and a significantly reduced duration in the light box in the light/dark box test, indicating obvious anxiety." (PMID 35241668, 2022). "The current results indicate that repetitive and anxiety-like behavioral deficits are observed in adult male and female Chd8+/S62X mice, whereas hypoactivity and excessive mother seeking/attachment are mainly observed in juvenile Chd8+/S62X males." (PMID 36385756, 2022). "Following gavage with B. uniformis, the Chd8+/− mice showed an increased proportion of time in the center in the open-field test and a significantly increased time in the light box in the light/dark box test, indicating the decreased anxiety-like behavior." (PMID 35241668, 2022). "Furthermore, CHD8 knockdown resulted in abnormalities in brain structure, increased anxiety levels, and aberrant social interactions in adult mice." (PMID 35726297, 2022). "However, Chd8+/S62X mice spent less time in the center region of the open-field area compared with WT mice, suggestive of anxiety-like behavior, as supported by a significant genotype difference." (PMID 36385756, 2022). "Therefore, adult male and female Chd8+/S62X mice display differential increases in anxiety-like behaviors." (PMID 36385756, 2022). "To explore whether behavioural phenotypes may be exacerbated in the Chd8neo/neo mild hypomorphs compared to Chd8+/− mice, we assessed socio-communicative, repetitive, anxiety and motor behaviours." (PMID 33627187, 2021). "Chd8+/∆SL mice exhibited anxiety-like behavior in three different tests." (PMID 33933000, 2021). "Modeling ASD-relevant behavior in mice presents significant challenges, and for Chd8+/– mouse models results have been highly variable, with some studies suggesting social deficits and anxiety behaviors while others have found minimal phenotypes in these behaviors." (PMID 33837267, 2021). "Furthermore, we and others have found that heterozygous deletion of Chd8 in mice results in altered social behavior, increased anxiety-like behavior, and cognitive deficits reminiscent of those seen in humans with CHD8 mutations." (PMID 33228730, 2020). "In addition, Chd8+/S62X mice spent less time in open arms of the elevated plus-maze and more time in the closed arms, as supported by the genotype difference, further suggesting enhanced anxiety-like behaviors in adult Chd8+/S62X mice." (PMID 36385756, 2022). "We next examined anxiety-like behavior and abnormal social behavior typical of ASD model mice, including CHD8-haploinsufficient mice." (PMID 37268684, 2023). "Next, we explored whether the Chd8+/− mice exhibited ASD-like behaviors, including impaired social interaction, anxiety, learning and memory deficits, stereotyped behavior, and depression." (PMID 35241668, 2022). "For behavioral tests, co-housing improved the anxiety-like behavior and social interaction behavior, but failed to improve the learning and memory deficits of Chd8+/− mice." (PMID 35241668, 2022). "S-benzyl-L-cysteine failed to recover the learning and memory deficits of the Chd8+/− mice but improved their impaired social interaction and anxiety, similar to the effect of B. uniformis." (PMID 35241668, 2022). "We showed general anxiety phenotype in Chd8+/∆SL mice regardless of sex, the depressive phenotype in Chd8+/∆SL female mice only and bidirectional social deficit in female and male mice." (PMID 33933000, 2021).
Anxiety (continued). "This suggests that Chd8+/∆SL mice prefer to stay in the dark after starting in the light zone, i.e., anxiety is higher in Chd8+/∆SL regardless of sex." (PMID 33933000, 2021). "Furthermore, Chd8 CKO male mice manifested increased anxiety-like behavior in the open-field test, but not in the elevated plus-maze test and the light-dark transition test." (PMID 37268684, 2023).
Intellectual disability (24 papers, 2015 to 2025). "A recent cohort study showed that pathogenic variants of CHD8 contribute to a broad range of phenotypic abnormalities, such as intellectual disability (68%), muscle hypotonia (29%), and a wide array of behavioral disorders (88%)." (PMID 39685474, 2024). "The largest study to date reported intellectual disability in 68%, macrocephaly in 53%, tall stature in 50% and behavioural abnormalities in 88% of individuals with likely pathogenic CHD8 variants." (PMID 38288845, 2024). "Since macrocephaly is more strongly related to ASD than to intellectual disability (ID) and many hcASD genes such as CHD8 and WDFY3 cause dysregulation of proliferation and brain overgrowth, what other fetal mechanisms are altered by excess proliferation that lead to an ASD outcome?" (PMID 29934544, 2019). "However, despite these findings, no learning and memory deficits could be detected in these mice and the relevance of these observations to the intellectual disability associated with CHD8 deficiency remains unclear." (PMID 38288845, 2024). "KDM6B mutations are linked to a neurodevelopmental disorder that includes developmental delay, autistic features and intellectual disability, consistent with a possible mechanistic relationship between CHD8 and KDM6B." (PMID 38288845, 2024). "CHD8 (chromodomain helicase DNA-binding protein 8) is one of the most commonly mutated genes in patients with ASD, bipolar disorder, schizophrenia and intellectual disabilities." (PMID 34886158, 2021). "CHD8 gene mutations in other disorders, such as CHD8-related neurodevelopmental disorder with overgrowth, have been implicated in ASD, intellectual disability, developmental delay, neuropsychiatric issues, neurologic problems, sleep disturbance, and gastrointestinal issues." (PMID 40984926, 2025). "The gene encoding chromodomain helicase DNA binding protein 8 (CHD8) has one of the highest observed mutation rates in sporadic ASD, and mutations to CHD8 have also been identified in cases from schizophrenia and intellectual disability cohorts." (PMID 30692911, 2018). "For example, the low pH/high lactate group included SZ model Nrgn KO mice, SZ/intellectual disability (ID) models Ppp3r1 KO mice and Hivep2 (also known as Shn2) KO mice, AD model APP-J20 Tg mice, ASD model Chd8 KO mice, and social defeat stress-induced depression model mice." (PMID 38529532, 2024).
Macrocephaly (19 papers, 2015 to 2025). Occipitofrontal (head) circumference greater than 97th centile compared to appropriate, age matched, sex-matched normal standards. "For example,CHD8 germline variants commonly cause macrocephaly, and Participant 1 with a somaticCHD8 variant also showed macrocephaly." (PMID 40182320, 2025). "In ASD patients with CHD8 de novo mutation, neurodevelopmental disorders and macrocephaly were observed, indicating CHD8 is associated with the brain development in human." (PMID 34686651, 2021). "Humans with truncating mutations in a single CHD8 allele often present with macrocephaly (64%) and distinct craniofacial phenotypes (89%), which include hypertelorism (wide-set eyes, 67%)." (PMID 29668850, 2018). "Intriguingly, 80% of affected individuals carrying likely causative CHD8 alleles exhibit macrocephaly, a significantly higher percentage than overall macrocephaly presentation in ASD cases of the SSC without CHD8 mutations, possibly defining a subtype." (PMID 27014681, 2016). "Further work is needed to clarify how CHD8 regulates Wnt signaling in different cell types in the brain, and how patients with CHD8 mutations acquire macrocephaly." (PMID 27980692, 2016). "Conversely, macrocephaly has been shown to occur in a subset of ASD patients harboring disruptive mutations in the ASD-linked chromodomain helicase DNA binding protein 8 (Chd8) gene or deletions in 17q12." (PMID 26483618, 2015). "To examine whether CHD8 mutations caused macrocephaly, we carefully examined the brain size of the CHD8 mutant monkeys (M2 and M3)." (PMID 36878905, 2023). "Whether this is the underlying mechanism for macrocephaly associated with CHD8 mutations and whether it is generalizable to the macrocephaly in other idiopathic ASD cases remain to be investigated." (PMID 30574290, 2018). "In addition, the mechanism underlying CHD8 deficiency-mediated macrocephaly remains controversial." (PMID 36878905, 2023). "Excessive growth of NPCs due to mutations in genes such as SUV420H1, CHD8, and PTEN associated with ASD risk and macrocephaly." (PMID 40255860, 2025). "Interestingly, among the three CHD8 PTVs identified in this study, two were de novo events while the third was inherited from a parent whose sole phenotypic feature was macrocephaly." (PMID 32094338, 2020). "Strikingly, 80% of individuals with mutations in CHD8 alleles display macrocephaly, which composes a much higher percentage of total macrocephaly cases in ASD patients without CHD8 mutations." (PMID 29209173, 2017).
schizophrenia (12 papers, 2015 to 2023). A major psychotic disorder characterized by abnormalities in the perception or expression of reality. "Functionally disruptive mutations in CHD8 have been reported in multiple ASD patients as well as one sporadic schizophrenia patient." (PMID 26491539, 2015). "Highly penetrant mutations in CHD8 might make an even better case for ESC/iPSC-based disease modeling than highly polygenic diseases like schizophrenia." (PMID 33477995, 2021). "Relatedly, gene sets reflecting neurodevelopmental processes implicated in schizophrenia and ASD, including the CHD8, FMRP, and RBFOX pathways, were also implicated in GCA." (PMID 34035472, 2021). "The loss of CHD8 expression could be a novel indicator for these disorders and CHD8 ASD patient should be screened for early signs of gastric or colorectal cancer, schizophrenia or other related psychosis disorder, such as depression and anxiety." (PMID 32309624, 2020). "There was significant heterogeneity among the gene sets, with the TCF4 gene set, the FMRP gene set, the gene set upregulated in the presence of excess MIR137 and the gene set downregulated in the absence of CHD8 shown to be associated with schizophrenia." (PMID 31078131, 2019). "Using the PGC2 secondary analysis schizophrenia case-control cohort (N = 29,125 cases and 34,836 controls), a robust polygenic signal was observed from gene sets based on TCF4, FMR1, upregulation from MIR137 and downregulation from CHD8." (PMID 31078131, 2019).
CHARGE syndrome (10 papers, 2014 to 2025). CHARGE syndrome is a multiple congenital anomaly syndrome characterized by the variable combination of multiple anomalies, mainly Coloboma; Choanal atresia/stenosis; Cranial nerve dysfunction; Characteristic ear anomalies (known as the major 4 C's). "CHD8 and its paralog CHD7 have been previously linked to the CHARGE syndrome in which renal anomalies have been described." (PMID 39350038, 2024). "Also, genetic disorders such as CHARGE syndrome support the hypothesis of common genetic risk factors for ASD given that CHARGE syndrome is due to mutations in CHD7, which is a homolog of CHD8, one of the most recurrently affected genes in autism cohorts." (PMID 25136320, 2014). "Unlike CHD8 and WHSC1, CHD7 has been previously implicated in neurocristopathy (CHARGE syndrome) and the motility of NCCs." (PMID 33554859, 2021).
developmental delay (9 papers, 2017 to 2025). "The mutations of CHD8 gene have significant role in ASD as studied in two unrelated children with developmental delay, and normal brain as shown using MRI." (PMID 32309624, 2020). "CHD8 was further evaluated as an ASD candidate gene in children with developmental delay or ASD, and 15 independent mutations were identified and enriched in a subset of ASD with altered brain size, distinct facial features and gastrointestinal complaints." (PMID 28702161, 2017). "Contrariwise, a Chd8 germline mutation may enable a compensatory response that overcomes early developmental delay." (PMID 33477995, 2021). "Human patients with CHD8 mutations present with typical autistic behaviors and comorbidities including social deficits and communication difficulties, repetitive behaviors and interests, and cognitive delays." (PMID 30574290, 2018). "Another patient with a de novo balancing translocation disrupting CHD8 presented with autistic features, developmental delay, and language disability at 2 years age." (PMID 33477995, 2021). "We identified a novel de novo loss-of-function CHD8 mutation in a Saudi child diagnosed with ASD and developmental delay." (PMID 32309624, 2020). "Bernier and colleagues re-sequenced the CHD8 gene in 3730 children with developmental delay or ASD and identified 15 mutations in CHD8 that were considered potentially disruptive." (PMID 28680792, 2017). "CNV deletions affecting CHD8 and SUPT16H were initially described in children with developmental delay and dysmorphic features." (PMID 29693535, 2018).
colorectal cancer (8 papers, 2017 to 2023). A primary or metastatic malignant neoplasm that affects the colon or rectum. "Loss of CHD4 expression was found in 56.4% of gastric cancers and in 55.7% of colorectal cancers, whereas CHD8 was mutated in 35.7% of gastric cancers and in 28.6% of colorectal cancers." (PMID 37175555, 2023). "Interestingly, CHD8 is mutated in breast cancer, gastric cancers, colorectal cancers, and prostate cancer, diseases associated with aberrant cell proliferation." (PMID 35365720, 2022). "In colorectal cancer and melanoma, BACH1 heterodimerizes with MAF BZIP Transcription Factor G (MAFG), cooperating with chromodomain helicase DNA-binding protein 8 (CHD8) and DNA Methyltransferase 3 Beta (DNMT3B) to inhibit the transcription of many antioncogenes." (PMID 35651942, 2022). "In addition, one gene, DCC (deleted in colorectal carcinoma), which was not differentially expressed in the previous study, was significantly decreased in CHD8+/− organoids." (PMID 28321286, 2017).
breast carcinoma (7 papers, 2014 to 2025). "In proliferating T47D breast carcinoma cells, CHD8 is mostly associated with promoters." (PMID 25894978, 2015). "However, CHD8 is one of the top tumor suppressor genes, mutated in breast cancer." (PMID 41278204, 2025). "The evidences include: overexpression of MCM2 in gastric tumors predicted poor prognosis in the patients; knock down of HJURP reduced the sensitivity of breast cancer patients to radiation treatment; the loss of CHD8 may be an indicator for biological aggressiveness in gastric cancer." (PMID 25390899, 2014). "To identify the genome-wide distribution of CHD8 in proliferating human breast cancer cells T47D-MTVL, we performed chromatin immunoprecipitation of CHD8 followed by deep sequencing (ChIP-seq)." (PMID 25894978, 2015). "CHD8 is a member of subfamily III with the strongest link to breast cancer." (PMID 41278204, 2025). "Based on this, the human TNBC cell line MDA-MB-231 was chosen due to strong expression of BCL11A and CHD8, and the luminal breast cancer cell line MCF-7 was selected as a control due to expression of CHD8 but no BCL11A expression." (PMID 40328966, 2025). "To further explore the expression of CHD8 in TNBC we analysed PDX samples which identified that, at the protein level, BCL11A and CHD8 are specifically upregulated in TNBC PDXs but not in Luminal breast cancer PDXs." (PMID 40328966, 2025). "In the BRCA samples of TCGA, we also noticed a significant relationship between AGR2 expression and FOXA1 gene copy number, as well as several cancer gene copy numbers localized at 14q such as NFKBIA, SAV1, CHD8 or AJUBA, which are not known as driver oncogenes or TSG in breast cancer." (PMID 35857928, 2022).
depression (6 papers, 2019 to 2025). "Candidate biomarkers including CHD8, DDX42, and EIF3D should be assessed in larger, independent cohorts of patients with PAH, with and without depression, as well as in MDD cohorts, to determine their diagnostic or prognostic potential." (PMID 41280439, 2025).
cognitive deficits (5 papers, 2022 to 2025). "Moreover, ASD-related condition linked to mutations in CHD8 is under investigation, extending the therapeutic landscape to complex behavioral and cognitive disorders." (PMID 41244709, 2025). "Autistic individuals with LoF variants in the four moderate-risk genes (NAV3, ITSN1, SCAF1 and HNRNPUL2; n = 95) have less cognitive impairment than 129 autistic individuals with LoF variants in highly penetrant genes (CHD8, SCN2A, ADNP, FOXP1 and SHANK3) (59% vs 88%, P = 1.9 × 10−6)." (PMID 35982159, 2022).
melanoma (5 papers, 2018 to 2022). A malignant, usually aggressive tumor composed of atypical, neoplastic melanocytes.
Rett syndrome (5 papers, 2020 to 2025). A severe neurodevelopmental disorder affecting the central nervous system.
lung carcinoma (4 papers, 2015 to 2022). "The results indicated that the remaining genes, apart from CHD1 and CHD8, were strongly linked to preimmune stages in lung cancer." (PMID 35467222, 2022). "While multiple groups have measured higher CHD8 expression in cancer cells than normal adult tissue, other groups have observed loss of expression in gastric and colorectal cancers and deletion in lung cancer." (PMID 26588464, 2015). "Parallel evolution has been shown in a variety of neoplasms, including lung cancers involving genetic alterations in the MUC1, CDK4, CHD8, and NKX2‐1 genes." (PMID 32333643, 2020). "Then, we selected CHD7 and CHD8, two members of subclass III whose biological function remains largely unknown in lung cancer, for subsequent pathway and function enrichment in LUAD and LUSC." (PMID 35467222, 2022).
cervical carcinoma (3 papers, 2014 to 2015). A carcinoma arising from either the exocervical squamous epithelium or the endocervical glandular epithelium. "We have previously reported that CHD8 binds 1965 promoters in a ChIP-on-chip analysis of proliferating cervical carcinoma C33 cells." (PMID 25894978, 2015). "Others have shown that CHD8 knockdown in cervical carcinoma cells leads to G1 arrest facilitated by downregulation of CCNE2 and TYMS, genes required for transition into S phase." (PMID 26588464, 2015). "We have recently reported a promoter ChIP-on-chip analysis demonstrating that, in cervix carcinoma C33 cells, CHD8 binds around 2000 active promoters also enriched in H3K4me2 and H3K4me3, and that it is required for expression of E2F-dependent G1/S transition genes." (PMID 25894978, 2015). "Furthermore, using ENCODE ChIP-seq data, we found that 32% of CHD8 target promoters were occupied by E2F1 in HeLa cells (P = 3.3 × 10−57), another cervical carcinoma cell line." (PMID 24265227, 2014).